RNU6-555P (RNA, U6 small nuclear 555, pseudogene)
Gene: Small nuclear RNA gene on chromosome X (90,597,235 to 90,597,340, reverse strand). Ensembl gene ENSG00000207515.
Homologues: Orthologues: chimpanzee U6 (98% identical), macaque U6 (92% identical), guinea pig U6 (80% identical), mouse Gm22305 (79% identical), pig U6 (76% identical), dog U6 (73% identical). Paralogues in human: RNU6-303P (98% identical), RNU6-589P (88% identical), RNU6-1011P (87% identical), RNU6-1122P (86% identical), RNU6-891P (86% identical), RNU6-1042P (85% identical), RNU6-116P (85% identical), RNU6-15P (85% identical), RNU6-166P (85% identical), RNU6-259P (85% identical), RNU6-41P (85% identical), RNU6-44P (85% identical), and 1285 more.